APP (amyloid beta precursor protein)
Diseases named in the same sentence as APP in open-access papers (continued):
Sharing a sentence is not in itself a finding about the gene and the disease.
Down syndrome (continued). "Overexpression of the amyloid precursor protein (APP) gene is associated with familial aggregation of late onset AD and dramatically increases susceptibility to early AD in Down’s syndrome." (PMID 29312321, 2017). "This is observed in trisomy 21 (Down syndrome) in humans, and trisomy 16 in mice, where an additional copy of the chromosome harboring APP is found." (PMID 28682239, 2017). "Humans with trisomy 21 (Down's syndrome) harbor 3 copies of APP and invariably develop neuropathologically typical AD." (PMID 27025652, 2016). "The amyloid precursor protein (APP) gene is over-expressed in Down syndrome (trisomy 21) as it is located on chromosome 21." (PMID 27473843, 2016). "APP (located in DSCR, 21q21.3) codes for the amyloid precursor protein, a hallmark of Down syndrome, whose overexpression severely affects thymic functions." (PMID 26848775, 2016). "Duplication of the wild‐type APP gene in Down's syndrome leads to Aβ deposits in the teens, followed by microgliosis, astrocytosis, and neurofibrillary tangles typical of AD." (PMID 27025652, 2016). "In Down syndrome (DS) or trisomy of chromosome 21, the β-amyloid (Aβ) peptide product of the amyloid precursor protein (APP) is present in excess." (PMID 27023444, 2016). "Consistent with Aβ toxicity being concentration-dependent, Down’s syndrome is characterized by APP overexpression due to trisomy 21 leading to an extra copy of the APP gene." (PMID 27809888, 2016). "The involvement of the APP gene has been discovered in patients with Down syndrome who are prone to develop AD at a very early age." (PMID 26041981, 2015). "A Down syndrome mouse model that includes a triplication of the APP gene shows degeneration of the locus coeruleus neurons with aging, which has been linked to the overexpression of APP." (PMID 26136654, 2015). "APP gene triplication in Down’s syndrome and APP locus duplication in rare families lead to clinical AD-like pathology in adults and result in early-onset dementia." (PMID 25862638, 2015). "In Down’s syndrome the abundant cerebral deposition of Aβ is attributed to excess APP synthesis due to the extra copy of chromosome 21 where the APP gene is located." (PMID 25618528, 2015). "Of significance, children suffering from Down’s syndrome that have an increased expression of APP have a reported high risk of iron deficiency and anemia, however, further investigation is required to confirm whether this is due to an increase in APP facilitated iron efflux." (PMID 24795635, 2014). "Down’s syndrome patients, whose chromosome 21 trisomy includes trisomy of APP, display a high incidence of AD and intellectual disability, perhaps contributed in small part by the high levels of APP expression." (PMID 25250042, 2014). "Seizures are very common in APP duplication and Down syndrome that have an extra copy of APP, thus reflecting a possible link between Aβ dosage and epilepsy." (PMID 24377094, 2013). "The ratio of APP-CTFs to flAPP is higher in brain exosomes compared to brain homogenates in both Down's syndrome and controls." (PMID 26082317, 2013). "Down’s syndrome sufferers, because of the extra gene copy of APP, invariably present with Alzheimer-type symptoms and pathology." (PMID 22654716, 2011). "Individuals with Down’s syndrome or Trisomy 21 have a replication of all or part of chromosome 21 (containing the APP gene), and thus an increase in APP gene dosage." (PMID 22654716, 2011). "Duplication of the APP gene, as the result of rare chromosomal duplications or, as in the case of Down's syndrome, duplication of the entire chromosome 21, is strongly associated with early-onset AD." (PMID 22013986, 2011). "Although no plaque pathology has been described, the APP8.9 mouse should recapitulate the APP dosage imbalance found in Down Syndrome." (PMID 21912750, 2011). "There are three copies of the APP gene in Down syndrome and the level of APP transcript in the brains of afflicted individuals is increased about 4.5-fold." (PMID 20205906, 2010).
Down syndrome (continued). "Intraneuronal Aβ accumulation has been identified in Down syndrome and AD patients, amyloid precursor protein (APP) and PS1 Presenilin 1 transgenic mice, and cultured cells." (PMID 20478062, 2010). "In Down Syndrome an additional copy of chromosome 21, which harbors the APP gene, leads to overexpression of APP protein, elevated Aβ levels, plaque deposition and AD-like disease in all older Down's patients." (PMID 20559548, 2010). "A major clue was given by Down's syndrome, in which trisomy of chromosome 21 results in early onset of AD, but not in a case in which chromosome 21 had a mosaic deletion of the amyloid precursor protein (APP) locus." (PMID 20126538, 2010). "People affected with Down’s syndrome (trisomy 21) display early signs of AD-like behavior, presumably due to gene (APP) dosing effect as APP gene is located in chromosome 21." (PMID 21369424, 2010). "For instance, Down’s syndrome patients who have three copies of APP, have CAA as young as 30 years and the severity of CAA increases with age." (PMID 19468344, 2009). "Intriguingly, in a trisomic mouse model of Down's syndrome deletion of one copy of APP led to a marked improvement in transport of signaling endosomes containing NGF, reduced neurodegeneration, and improved cognitive function." (PMID 19348680, 2009). "At the genomic level, Down's Syndrome (Trisomy 21) patients have three copies of the APP gene and develop AD symptoms early in life." (PMID 18684319, 2008). "Excessive GABA-mediated inhibition was reported in the Ts65Dn mouse model of Down syndrome (DS), which expresses three copies of chromosome 16 genes like APP, GluR5, etc.." (PMID 18716656, 2008). "Interestingly, in Down syndrome, patients have an extra copy of chromosome 21, which includes the APP gene." (PMID 39757377, 2025). "The possibility that APP overexpression could lead to hyperexcitability made us interested in mouse models of Down syndrome." (PMID 40599392, 2025). "Qualitative differences in staining between early and late onset AD cases were however noted: in both Down syndrome and familial AD, dystrophic neurites that stained intensely for APP in neuritic plaques were frequent, whilst similar features were rare in late onset AD." (PMID 39084860, 2025). "The study focuses on differences observed between rare and poorly studied patient groups with APP duplications (APPdup) and Down syndrome (DS) reported to have higher frequencies of elevated CAA levels in comparison to sporadic AD (sAD), most of APP mutations, and controls." (PMID 39026031, 2024). "Some individuals with Down syndrome have a translocation that eliminates the APP gene in the replicated portion of the gene, and these individuals are less likely to develop the neuropathologies associated with AD than those who do not have such a translocation." (PMID 37344566, 2023). "Variation amongst individuals with Down syndrome informs the role of APP in the development of AD." (PMID 37344566, 2023). "When scientists cloned APP, they quickly learned that the gene is located on chromosome 21, a finding that was important because patients with trisomy 21 have Down syndrome and invariably develop neuropathological and clinical signs of early-onset AD, starting in their 40s or earlier." (PMID 35862308, 2022). "This hypothesis has been formulated after having identified the APP gene on chromosome 21, together with the observation that people affected by Down syndrome develop AD-like symptoms early in life." (PMID 33921556, 2021). "The production of APP increases in some physiological conditions, such as during neuronal maturation and differentiation, and in some pathological ones, including AD, brain trauma, and Down syndrome." (PMID 33921556, 2021). "Moreover, APP overproduction, either as a result of genomic locus duplication in Down Syndrome or altered regulatory sequences in the APP promoter region, leads to early-onset AD in humans." (PMID 33311478, 2020).
Down syndrome (continued). "Possession of extra wild-type copies of APP, such as found in Down Syndrome (DS) or in rare individuals without DS, is also associated to early-onset AD." (PMID 32580938, 2020). "Notably, lower levels of soluble Aβ and α-syn are present even in patients with APP gene duplication in Down syndrome and SNCA gene duplication in familial PD." (PMID 32372895, 2020). "Interestingly, during iPS cell differentiation to neurons, APP-3′AS shows an opposite regulation compared to intragenic antisense ncRNAs, being upregulated at later differentiation stages (5-fold induction in Down Syndrome cells)." (PMID 30610612, 2019). "As summarized in review papers, clinical studies found that NFTs appeared following amyloid deposition in Down syndrome (carrying an extra copy of APP) and an increase in CSF tau following amyloid deposition in early onset cases with inherited mutations of APP and presenilin." (PMID 31011484, 2019). "Over decades, disruption of homeostatic Aβ entry and clearance could eventually result in brain plaque formation, analogous to the early onset of Aβ brain deposits in Down’s syndrome due to whole-body overexpression of APP." (PMID 30192871, 2018). "Tau phosphorylation, however, was unchanged in neurons derived from patients with a PSEN1 mutation and a recent study demonstrated that the increase in tau phosphorylation observed in neurons derived from a patient with Down’s syndrome was unchanged following correction of the APP gene dosage." (PMID 30387070, 2018). "Interestingly, a common pathology of APP duplications and Down syndrome is intracerebral hemorrhage suggesting that increased APP expression disrupts the integrity of brain vasculature." (PMID 30150923, 2018). "Also in Down’s syndrome patients, where there is an extra copy of chromosome 21, which carries the APP gene, there is increased production of APP and these individuals all develop Alzheimer’s like disease." (PMID 30509933, 2018). "In addition to monogenic fAD models, APP dosage models have been shown to demonstrate similar changes in APP processing to patients with APP duplication and Down’s syndrome (trisomy of chromosome 21 on which APP resides)." (PMID 28610595, 2017). "Aβ is the major constituent of the tissue deposits found in parenchymal plaques and cerebral blood vessels of patients with AD and with Down's syndrome, the latter exhibiting a trisomy in chromosome 21 which codes for the Amyloid Precursor Protein (APP) and lead to AD pathology by middle age." (PMID 27729857, 2016). "Indeed the few reports of people with Down syndrome who carry only two copies of the APP gene due to a deletion of one copy of the APP gene on one of their three copies of chromosome 21 indicate a lack of Alzheimer-like dementia even at age 60+." (PMID 29516054, 2016). "In this research, APP was up-regulated that implied its potential role in Down Syndrome." (PMID 27266699, 2016). "The original formulation of the amyloid hypothesis was based in part on the discovery that the APP gene is on chromosome 21, implying that individuals with Down's syndrome develop typical Alzheimer neuropathology because they produce too much Aβ lifelong." (PMID 27025652, 2016). "However, it has been shown that development of AD pathology is associated with a 1.5-fold or more increase of expression of APP in Down’s syndrome patients and a twofold increase in patients with APP gene duplication." (PMID 25869641, 2015). "Similarly, Trisomy 21/Down syndrome neurons, in which there is an additional copy of the APP gene, were found to increase production of Aβ peptides, which lead to the accumulation of Aβ in extracellular aggregates." (PMID 24939911, 2014). "Thus, high-level secretion of exosomes enriched with the APP-CTFs suggests a mechanism for the early onset of Alzheimer's disease, including deposition of amyloid β, in Down's syndrome patients." (PMID 26082317, 2013).
Down syndrome (continued). "Down syndrome patients invariably develop AD, which may be due to additional gene dose of the APP gene in the Down critical region of chromosome 21." (PMID 23368879, 2013). "Furthermore, Down syndrome (DS) patients carry three copies of chromosome 21 which includes the APP gene locus, and therefore, DS patients have a “genetic overdose” of APP, leading them to develop AD by middle age." (PMID 22534039, 2012). "The gene for APP also is present on chromosome 21, and in Down syndrome individuals, the increase dosage of APP might be responsible for the observation of AD-like pathology in these individuals, if they live long enough." (PMID 22312456, 2011). "Furthermore, persons affected by Down's syndrome (trisomy-21), who have three copies of chromosome 21 and therefore the APP gene, inevitably develop AD." (PMID 16930455, 2006). "Moreover, within the S100 protein family, it is important to mention that the S100B (encoded by a gene located on the chromosome 21) was shown to be involved in APP processing, protein inclusion formation, and tau post-translational modifications in Down syndrome." (PMID 36394661, 2023). "Furthermore, Down Syndrome patients demonstrate a similar buildup of plaques, neurofibrillary tangles, inflammation and oxidative stress as seen in AD patients, and this is believed to be due to triplicate expression of APP." (PMID 34209883, 2021). "The amyloid cascade hypothesis suggests that this increased risk is due to the supernumerary copy of the amyloid precursor protein (APP) gene that is present in Down's syndrome, which in turn is posited to increase the levels of beta‐amyloid (Aβ) present in the brain." (PMID 31350817, 2019). "Specifically, we have found that the A peptide, encoded by the amyloid precursor protein (APP) gene that resides on chromosome 21, can induce large, permanent changes in the genome with potentially wide-ranging effects on gene expression, and, thus, on phenotypes in people with Down syndrome." (PMID 29516054, 2016). "However, in recent years, similar phenotypes have been reported for AD mouse models based on APP overexpression and disturbances of axonal transport rates have been reported in APP-based transgenic mouse models of Down syndrome and AD." (PMID 25018730, 2014). "Conversely, mouse models of Down syndrome that lack the APP gene still exhibit some of the AD-like pathologies, suggesting that duplication of the APP gene might not be the only cause of early-onset AD in Down syndrome individuals." (PMID 24396150, 2014). "In addition to these two mouse models of Down syndrome, transgenic mice have been generated that harbor an additional copy of a mutant form of APP (K670M/N671L) that has been identified in a Swedish family with early-onset AD (‘APP overexpression’)." (PMID 24396150, 2014). "App mRNA codes for a transmembrane protein amyloid-beta protein precursor (APP), which is processed by β- and γ-secretases to generate amyloid-beta (Aβ), the predominant protein found in the senile plaques characteristic of Alzheimer’s disease (AD) and Down syndrome." (PMID 23754978, 2013). "Similarly, the reduced neurogenesis and reduced neuronal number in Down syndrome, may result from the constitutive over expression of APP and production of Aß and the consequent induction of the cell cycle defect of chromosome mis-segregation." (PMID 23593294, 2013). "The identification of rare genetic mutations in the amyloid precursor protein (APP), and the presenilins (PS1, PS2), as well as Trisomy 21 (Down syndrome, DS), that invariably lead to AD pathogenesis support the hypothesis that Aβ is an early, key player in the disease." (PMID 24148220, 2013). "Germline APP single-nucleotide variations and copy number variations are considered causal in rare familial AD, consistent with APP trisomy producing AD neuropathology in Down syndrome (DS); however, APP germline alterations are absent in sporadic AD, which is the most common form." (PMID 38675371, 2024).
Down syndrome (continued). "In order to research AD in early-onset Down syndrome patients, CRISPR-Cas9 was utilized to remove the extra copy of APP from the T21 lineage, and inducible CRISPRa was employed to boost APP gene expression." (PMID 38031028, 2023). "Expression levels of Down syndrome-related genes such as SOD1, DYRK1A, ETS2, APP, and DSCR1 in chromosome 21 are comparable with the gene number, i.e., three 21 chromosomes." (PMID 30760866, 2019). "Finally, it is obvious that all types of APP FAD mutations as well as the protective Icelandic mutation or the presence of AD in Down syndrome patients with an APP gene triplication are not explainable by the presenilin hypothesis." (PMID 31225454, 2018). "Nevertheless, both mouse models carry most of the gene complement of the Down syndrome critical region, including RCAN1, APP, SOD1 and DYRK1A." (PMID 30034324, 2018). "The amyloid precursor protein (APP) is also coded in chromosome 21; therefore, with the extra copy of chromosome 21, Down syndrome (DS) patients have three copies of DYRK1A and APP explaining why most individuals with DS show early-onset of AD32." (PMID 26888634, 2016). "The amyloid precursor protein (APP) gene is located on chromosome 21 and thus is overexpressed in Down syndrome (trisomy 21), leading to amyloid β (Aβ) overproduction." (PMID 24888381, 2014). "Down's syndrome (DS) patients, who have an extra copy of the APP gene on chromosome 21, and FAD families with a duplicated APP gene locus, exhibit total Aβ overproduction and all develop early-onset AD." (PMID 18005427, 2007). "Down’s syndrome (DS) patients, who are trisomic for chromosome 21 and thus have an extra copy of the APP gene, and FAD families with a duplicated APP gene locus exhibit total Aβ overproduction and all develop early-onset AD." (PMID 19415126, 2007). "In addition, the amyloid hypothesis was extensively criticized because of many reasons, including that APP mutations in AD patients have a low frequency, many Down’s syndrome patients did not develop AD and the presence of presenilin mutations did not correlate with the increased Aβ production." (PMID 34066371, 2021). "Taken together, SGR maintains the central genetic importance of APP in familial forms of AD and Down syndrome but significantly extends it to account for SAD without requiring germline changes in APP." (PMID 32457796, 2020). "The first de novo duplication of the APP locus, not encompassing the critical Down syndrome region, has been recently reported in a patient with neuropathologically confirmed sporadic EOAD." (PMID 30478624, 2019). "This explanation is also unlikely, since in our peer-reviewed publication on Down Syndrome, also performed with MEMRI, we found increased transport with 1.5-fold expression of APP, a gene on the triplicated chromosome, and decreased numbers of cholinergic neurons in the basal forebrain." (PMID 31849608, 2019). "Rare individuals with translocation Down's syndrome involving only the distal part of chromosome 21 telomeric to the APP gene have Down's features but do not get AD." (PMID 27025652, 2016). "The amyloid hypothesis of AD suggests that AD results from dysregulation of the amyloid precursor protein (APP) gene on chromosome 21, analogous to the increase in brain amyloid in Down syndrome due to an extra copy of chromosome 21 (trisomy)." (PMID 26600964, 2015). "The APP duplication patchily involved almost the entire Chr21q, but critically did not include the Down's syndrome critical region around 21q22." (PMID 21193246, 2012). "Individuals who have Down's syndrome but lack the region of chromosome 21 containing the APP gene do not develop AD." (PMID 16930455, 2006). "However, in patients with Down syndrome, despite having a high APP and Aβ load, AD does not manifest in children or adolescents, and dementia typically emerges from around the fifth decade onwards." (PMID 39120323, 2024).